GARIN2 (golgi associated RAB2 interactor family member 2)
Description:
Seems to play a role in sperm motility.
Synonyms: C14orf54; FAM71D; GARI-L2; GARI-L1
Tractability: No criterion of Open Targets' tractability assessment is met for any kind of drug.
Gene: Protein-coding gene on chromosome 14 (67,189,393 to 67,228,550, forward strand). Ensembl gene ENSG00000172717.
Subcellular location: Cell projection, cilium, flagellum
Gene Ontology:
Biological process: flagellated sperm motility
Cellular component: sperm midpiece; motile cilium
Genetic constraint (gnomAD): Loss-of-function variants: 24 observed, 34.64 expected, observed/expected ratio (o/e) 0.69, 90% interval 0.5 to 0.97. The upper end of that interval is the gene's LOEUF score, 0.97, which puts it in group 4 of 6, group 1 being the genes least tolerant of losing a copy. Missense variants: 463 observed, 512.92 expected, observed/expected ratio (o/e) 0.9, 90% interval 0.84 to 0.98. Synonymous variants: 170 observed, 191.09 expected, observed/expected ratio (o/e) 0.89, 90% interval 0.78 to 1.01.
Homologues: Orthologues: chimpanzee GARIN2 (94% identical), macaque GARIN2 (77% identical), rabbit GARIN2 (71% identical), pig GARIN2 (67% identical), dog GARIN2 (67% identical), guinea pig GARIN2 (67% identical), rat Garin2 (58% identical), mouse Garin2 (57% identical). Paralogues in human: GARIN3 (25% identical), GARIN4 (23% identical), GARIN5B (21% identical), GARIN6 (17% identical), GARIN5A (15% identical), GARIN1B (14% identical), GARIN1A (13% identical).
Diseases named in the same sentence as GARIN2 in open-access papers:
GARIN2 is named in the same sentence as 2 diseases in open-access papers, as found by Europe PMC text mining. Sharing a sentence is not in itself a finding about the gene and the disease.
GARIN2 shares sentences with these, for which no sentence is quoted: Globozoospermia (2 papers); male infertility (2).